CDK1 (cyclin dependent kinase 1)
Diseases named in the same sentence as CDK1 in open-access papers (continued):
Sharing a sentence is not in itself a finding about the gene and the disease.
tumor (continued). "We have previously shown that treatment of brachyury-high tumor cells with the WEE1 inhibitor, MK-1775, is able to overcome tumor resistance to immune-mediated killing by decreasing WEE1 activity and increasing the level of functional CDK1." (PMID 29774202, 2018). "Alterations to cyclin D1, CDK1, CDK2, CDK4 and p16, which regulate the cell cycle, led us to speculate whether ABHD11‐AS1 affects tumour progression by regulating the protein expression of factors linked to the cell cycle." (PMID 29799152, 2018). "Conversely, increasing STIL could promote CDK1/CYCLIN B activity and indirectly participate in CYCLIN B-dependent proliferation in tumor cells." (PMID 29352115, 2018). "This means that when the expression level of CCNB1, CDC25C, CDK1 and PLK1 is reduced, the abilities in tumor cells proliferation could be inhibited at the same time." (PMID 29500418, 2018). "Interestingly, increased RNASEH2A and CD151 expression was observed in si-CDK1-treated ccRCC cell lines and were was found in RCC patients with a low tumor CDK1 level and bad clinical outcomes." (PMID 29843367, 2018). "CDKN1A (p21) gene expression was significantly lower in non-functioning tumours vs controls while CDK1 expression was high in all tumour types but only reached statistical significance in GH-secreting tumours." (PMID 28649092, 2017). "The in vitro results were confirmed in an in vivo xenografts, providing evidence of a greater inhibitory activity of pulsed supraphysiological T supplementation than continuous treatment, both in terms of tumor volume and decreased AR, p-ARser81, PSA and CDK1 staining." (PMID 29371946, 2017). "In addition, results from in vivo nude mouse xenograft tumor model showed that XIST knockdown reduced the tumor size, the protein levels of CDK1 and Cyclin D1 in tumors, and increased P21 protein level in tumors." (PMID 29371940, 2017). "Besides, different from CCNB1, CCNA1 functions in S and G2/M phases, which is due to its two different phosphorylated substrates, CDK1 and CDK2, subsequently conducing tumor cells proliferation." (PMID 26999101, 2016). "Interestingly, dinaciclib, an inhibitor against CDK1, 2, 5, and 9 (IC50 1-4nM), but with less activity against CDK4, 6, and 7 (IC50 60-100nM), showed encouraging anti-tumor effect in preclinical studies of TNBC with potential selectivity for MYC driven tumors." (PMID 27486754, 2016). "AT7519, a CDK1/2/4/5/9 inhibitor, showed the greatest selectivity for KRAS mutant tumour cells." (PMID 26881434, 2016). "The analysis in the non-isogenic tumour cell panel suggested that the CDK1/KRAS SL was a relatively hard synthetic lethal effect." (PMID 26881434, 2016). "On the other hand, when TAZ is overexpressed in tumor cells, there are not enough Cdk1 molecules in cells to phosphorylate and inactivate TAZ, which will cause resistance of tumor cells to antitubulin drug-induced apoptosis." (PMID 26183396, 2015). "There were no statistical differences in the expression of CDK1 protein and the clinicopathological features by age, gender and tumor location." (PMID 25129248, 2015). "CDK1 and CDK2, two cell cycle regulatory protein kinases that play important roles in cell cycle transitions, have been reported to phosphorylate FOXO1 and attenuate its tumor suppressor function." (PMID 25472505, 2014). "Using a combined geneset of these 5 remaining cell cycle-related genes (BUB1B, CCNB1, CCNB2, TTK and CDK1) as well as ADAM7 and FAM72B, we also observed a statistically-significant reduction in disease-free survival of patients with tumours exhibiting alterations in gene expression (p = 0.015)." (PMID 25519703, 2014). "There was no change in the phosphorylation of CDK1, WEE1 or in the total levels of CDK1 or WEE1 in the tumor samples (data not shown) as expected." (PMID 24661910, 2014). "Results show cell cycle genes differentiating current from never smokers in the early stage tumor tissue samples one of them being CDK1 gene." (PMID 22952714, 2012).
tumor (continued). "In a re-analysis of those data, one prominentgene-expression feature included genes regulating the cell-cycle (e.g. CCNE1,CDK1, CDC25A), and involved in DNA replication(e.g. POLE2, MCM4, TK1) andchromosome dynamics (e.g. SMC4, CENPE), ostensiblyreflecting tumor cell proliferation levels." (PMID 21629784, 2011). "The increase in CDK1 specific activity after paclitaxel treatment indicates that a tumor is sensitive to paclitaxel, and a lack of change in CDK1 indicates that a tumor is resistant to paclitaxel." (PMID 19239702, 2009). "Meanwhile, we observed a significant overlap in the expression patterns of key cell cycle regulators, including CDC25C, CCNB1, and CDK1, with PPIH in malignant cells, further suggesting that PPIH may promote tumor cell proliferation by modulating cell cycle progression." (PMID 40895540, 2025). "Of these hub genes, only four genes, CDK1, NDC80, KIF11, and COL4A2, were shared between the two groups, whereas 189 hub genes from the normal group replaced 101 different hub genes from the tumor group, resulting in protein–protein network differences between the normal and tumor groups." (PMID 40457491, 2025). "Identification of Core Targets: Five critical anti-GC targets (CDK1, CCNA2, TOP2A, CHEK1, and PLK1) were identified, with a focus on their roles in cell cycle regulation and chemotherapy resistance, providing mechanistic insights into Diosgenin’s anti-tumor effects." (PMID 40487391, 2025). "In‐depth studies have shown that CDK1 regulates tumor cell cycle control, and TK1, a rate‐limiting enzyme for DNA repair synthesis, is a known S‐phase‐dependent enzyme of the cell cycle and has been widely used as a serum marker for tumor cell proliferation dynamics." (PMID 39949984, 2025). "Therefore, we suggest the upregulation of genes in our model work together in regulating cell cycle and tumor progression, with HJURP ensuring chromosome stability, CDK1 driving mitotic entry, and FOXM1 promoting proliferation and CHEK1 supporting cell survival under DNA damage conditions." (PMID 40299539, 2025). "In addition, 113 hub genes from the normal group, 48 hub genes from the tumor group, and 2 hub genes (CDK1 and KIF11) from both groups were included in the 9427 DEG (p ≤ 0.001 and p ≤ padj) sets, indicating differential expression between the normal and tumor tissues." (PMID 40457491, 2025). "The convergence of these results emphasizes the interplay between tumor cell proliferation and immune responses, underscoring the potential for therapeutic strategies that leverage CD4+ T cells to enhance anti-tumor immunity while targeting key cell cycle regulators such as PLK1, CDK1, and CDC20." (PMID 39457373, 2024). "In addition, with the prolonged treatment of HepG2 cells with 20 μg/mL of the CXCL14 protein, the expression levels of pro-apoptotic genes BAK and BAX increased significantly, while the expression levels of tumor pro-proliferation genes HIF1A, mTOR and CDK1 decreased significantly." (PMID 37835641, 2023). "Single-cell sequencing revealed that CDK1 is mainly localized on tumor cells and macrophages; however, we could not clearly distinguish which specific type of macrophages contained CDK1." (PMID 36950551, 2023). "Notably, high expression of PIN1 (62/71, 87.32%) and CDK1 (60/71, 84.51%) were detected in most tumor specimens, while weak or none staining signals of pVHL was detected (55/71, 77.46%)." (PMID 36813923, 2023). "The interaction network showed that FOXM1 was closely correlated with those proteins who are involved in the cell cycle, such as cyclin-dependent kinase 1 (CDK1), CDK2, Cyclin B1 (CCNB1), as well as CCNB2, indicating FOXM1 may act as an important regulator of the tumor cell cycle." (PMID 37159818, 2023).
tumor (continued). "The results showed that HCT8‐OR and HT29‐OR‐bearing mice did not respond to oxaliplatin; however, when CDK1 was knocked out, the tumor mass was significantly reduced following oxaliplatin treatment, which was further verified by IHC staining of the Ki‐67 (a proliferation marker)." (PMID 37428466, 2023). "Higher activation of CDKs, including CDK1 and CDK4, was observed in EPCAM− tumour cells compared with in EPCAM+ and Rhoj-KO EPCAM− cells after chemotherapy suggesting that RHOJ enables EMT tumour cells to progress in the cell cycle and continue DNA synthesis after chemotherapy." (PMID 36949199, 2023). "In addition, CDK1 inhibitors could eliminate the effect of YOD1 overexpression (the proliferation and resistance to cisplatin), which further elucidates the tumor promoting mechanism of the YOD1-CDK1 axis." (PMID 37667382, 2023). "Similarly, although DASA-58 decreases Cdk1-cyclin B complex formation in tumor cells, it does not under normoxic conditions alter cell growth." (PMID 35392228, 2022). "CXCL8 and CDK1 may change G2-M transformation and EMT and promote tumor proliferation." (PMID 36078096, 2022). "The tumor-promoting effect of circ-NOLC1 was inhibited by knockdown of ESRP1, CDK1, or RhoA expression in circ-NOLC1-overexpressing cells, which might act by modulating RhoA and CDK1 expression." (PMID 33483472, 2021). "It has been demonstrated that after the application of different chemotherapeutic agents (cisplatin, camptothecin, etoposide, paclitaxel and vindesine), up to 10% of the tumour cells enter a non-proliferative state reversible upon the overexpression of cyclin-dependent kinase Cdc2/Cdk1." (PMID 34943822, 2021). "Indeed, inhibition of CDK1 with a highly selective small molecule CDK1 inhibitor RO-3306 has been shown to be more tumor specific rather than normal cell specific." (PMID 33805800, 2021). "Furthermore, TPX2, ZWINT, UBE2C, CCNB2, CDK1, BUB1, and BIRC5 may orchestrate the stemness, proliferation, and invasion of tumor cells." (PMID 34671679, 2021). "Moreover, overexpression of CDK1, CCNB1, CDC20, BUB1, MAD2L1, and BUB1B in tumour tissues could increase cell proliferation and division." (PMID 33035258, 2020). "Furthermore, CDK1 accumulation was positively correlated to the degree of tumor malignancy and showed a negative correlation with βTrCP." (PMID 33014840, 2020). "In all analyses, the prognostic value of the combination of Securin and Separase with or without Cdk1 outperformed the impact of tumor size and histological grade whereas axillary lymph node status remained a strong and independent prognosticator in all analyses." (PMID 32546141, 2020). "Selective inhibition of CDK1/2 and the core component BUD31 of restriction enzymes can induce apoptosis of TNBC tumor cells overexpressing MYC, suggesting that TNBC, especially the BL1 and M subtypes, might benefit from CDK1/2 and restriction enzyme inhibitor treatment." (PMID 32517735, 2020). "Our results showed that the tumor suppressors CDKN1A (also known as Cip1 and p21) and GADD45 were downregulated while various positive cell-cycle regulators and components for DNA replication, including cyclin-B, cyclin-D, CDK1, CDC25B, and MCMs, were upregulated by TSPY-overexpression." (PMID 30867900, 2019). "Furthermore, we found that gene expression of INPP4B, CDK1, and ERBB2 was statistically significantly connected with patient survival in the same manner as the commonly used reference genes ESR1 (for ER status) and MKI67 (for tumor grade or proliferation)." (PMID 31315058, 2019). "Similarly, in our study, CDK1 knockdown in RCC cell lines did not have a pronounced effect on tumor growth." (PMID 29843367, 2018).
tumor (continued). "E2F8 was found to be markedly overexpressed in HCC to facilitate tumor occurrence and development via activation of an E2F1/cyclin D1 signaling pathway to regulate the G1- to S-phase transition of cell cycle progression or transcriptionally suppress CDK1 to induce hepatocyte polyploidization." (PMID 30326936, 2018). "Taken together, these data suggest that the tumor suppressive effects of ERβ in TNBC are in part mediated by inhibition of genes involved in cell cycle progression and provide further support for the development of CDK1 and CDK7 specific inhibitors for the treatment of TNBC." (PMID 29228549, 2017). "The expression of CDK1, -4, and -6 was not changed in AM-1 cells, even with the induced overexpression of ameloblastin gene that may function as a tumor suppressor." (PMID 28357197, 2016). "The tumor prognosis in CDK1 positive group was obviously worse than that of CDK1 negative group." (PMID 25129248, 2015). "In addition, correlation of CDK1 expression and prognostic and the 5-year accumulative survival rate of OSCC were investigated.Results: The CDK1 protein was expressed in 52 cases of 77 tumor tissues (67.5%), compared with 21 cases of 60 controlled (35.0%)." (PMID 25129248, 2015). "Finally, we found that CDK1 accumulation in patients’ tumors shows a negative correlation with βTrCP and a positive correlation with the degree of tumor malignancy." (PMID 25149538, 2014). "Finally, we found that CDK1 accumulation in patients’ tumors shows a negative correlation with βTrCP levels and a positive correlation with the degree of tumor malignancy." (PMID 25149538, 2014). "With tumor progression, the original requirement for high level of CDK1 activation may not be necessary when more favorable genetic and epigenetic changes occur." (PMID 21887332, 2011). "In addition, the tumor-promoting effect of circ-NOLC1 was reduced after ESRP1, CDK1, or RhoA knockdown in circ-NOLC1-overexpressing cells, thus we hypothesized that circ-NOLC1 might function as an oncogene through binding and modulating ESRP1, CDK1, and RhoA levels." (PMID 33483472, 2021). "Interestingly, in BFTC909, CDK1 could not be knocked down after a 96-hour si-CDK1 transfection, and the tumor survival rate even increased." (PMID 29843367, 2018). "Synergistic inhibition of CDK1 and poly (ADP-ribose) polymerase (PARP), an abundant nuclear enzyme involved in DNA repair, was shown to prolong survival in a spontaneous mouse tumor model without apparent normal tissue toxicity." (PMID 33805800, 2021). "Further gene co-expression network analysis and prognostic analysis indicated CDK1, CCNB2, and CDC25A as the hub tumor-promoting genes in LUAD but not in LUSC, which were further validated in other datasets." (PMID 34446056, 2021). "Inhibition of WEE1 G2 checkpoint kinase (WEE1), a CDK1 negative-regulator, alongside PD1 blockade resulted in diminished tumour growth in two LUSC subcutaneous syngeneic models." (PMID 34354223, 2021). "CDK1 knockdown resulted in the upregulation of RNASEH2A and CD151 in all cell lines, however it did not significantly impair tumor proliferation (except for a mild effect on A704)." (PMID 29843367, 2018). "We found the extent of CDK1 phosphorylation at Thr161 to be enhanced in KRAS mutant cells compared to WT cells in the SW48 KRAS isogenic model, PDAC and CRC non-isogenic tumour cell lines." (PMID 26881434, 2016). "CDK1 was validated using a different KRAS isogenic cell model (SW48) as well as a series of non-isogenic CRC and PDAC tumour cell models." (PMID 26881434, 2016). "This analysis suggested that the CDK1/KRAS synthetic lethal effect was not restricted to isogenic systems but also operated in a variety of different, genetically diverse, KRAS mutant tumour cells." (PMID 26881434, 2016).
tumor (continued). "The cell cycle regulating proteins cdk1, cdk2 (not in KTC-26), cdk4 (not in A498), cyclin A and cyclin B were all down-regulated in the tumour cells when treated for 24 hrs with sunitinib." (PMID 25444514, 2015). "Nuclear CDK1 and TOP2A was exclusively expressed in tumor tissues compared to normal tissues, including non-pulmonary normal organs." (PMID 21887332, 2011). "Although immunohistochemical analyses of markers such as phosphorylated histone H3, γH2AX, and phosphorylated CDK1 have been employed to monitor CHK1 pathway activity, these assays require serial tumor biopsies, which are often not feasible in clinical settings." (PMID 40869030, 2025). "CDK1 accumulation in patients’ tumors shows a negative correlation with beta-transducing repeat containing E3 ubiquitin protein ligase (BTRC) and exhibits a positive correlation with the degree of tumor malignancy." (PMID 37311884, 2023). "In addition, the mRNA levels of CDK1 showed significant positive correlations with FGF20 in FAP(+) CAFs and FGFR2 in PanCK(+) tumor epithelial cells at EOCC tumor invasive margin, but not at LOCC tumor invasive margin." (PMID 37964075, 2023). "When tested in DR5‐treated tumor cell‐jurkat cell co‐culture reporter assays, inhibition of various posttranslational PD‐L1 stability regulators such as mTOR, STAT3, CDK1, and NF‐kβ did not change PD‐L1 surface expression." (PMID 33587338, 2021). "However, the fascinating observation of our study is that the hub genes including CDK1, CDK2, CCNB1, and HDAC1 and common genes including E2F3 identified in Rb tissues are well-known oncogenes that trigger cell cycle progression in tumor cells in the absence of RB1 gene." (PMID 35359459, 2022).